CT45A7 (cancer/testis antigen family 45 member A7)
Tractability: PROTAC: ubiquitination databases record sites on it.
Gene: Protein-coding gene on chromosome X (135,829,229 to 135,837,280, reverse strand). Ensembl gene ENSG00000273696.
Subcellular location (Human Protein Atlas): Nucleoli; Nucleoplasm
Homologues: Orthologues: rat Ct45a9 (29% identical), mouse Ct45a (28% identical), Caenorhabditis elegans ints-6 (17% identical), Drosophila melanogaster IntS6 (16% identical). Paralogues in human: CT45A5 (100% identical), CT45A6 (100% identical), CT45A3 (99% identical), CT45A1 (99% identical), CT45A2 (98% identical), CT45A8 (98% identical), CT45A9 (98% identical), CT45A10 (95% identical), SAGE1 (35% identical), INTS6L (31% identical), INTS6 (26% identical).
Diseases named in the same sentence as CT45A7 in open-access papers:
CT45A7 is named in the same sentence as 1 disease in open-access papers, as found by Europe PMC text mining. Sharing a sentence is not in itself a finding about the gene and the disease. The quoted sentences say what the papers report.
lung carcinoma (1 paper, 2015). "A related gene family member, CT45A7, has been reported to be expressed in lung cancer." (PMID 26335491, 2015).